MYC (MYC proto-oncogene, bHLH transcription factor)
Diseases named in the same sentence as MYC in open-access papers (continued):
Sharing a sentence is not in itself a finding about the gene and the disease.
leukemia (continued). "Moreover, MLL-FPs are able to form a molecular complex with BRD4 (an epigenetic reader), PAFc and SEC to sustain the oncogenic expression of BCL2, CDK6, and MYC in MLL-r leukemias." (PMID 31157223, 2019). "Both regions have been found to regulate MYC expression in mouse leukaemia cell lines." (PMID 30247654, 2019). "Altogether, these results support proscillaridin A repurposing against MYC overexpressing leukemia." (PMID 31196146, 2019). "They reported that combination of EPZ004777 and MI-2-2 (an inhibitor of MLL–Menin interaction) enhanced the down-regulation of important leukemia genes (i.e., MYC, HOXA9, and MEIS1) and anti-proliferative effects against MLL-r leukemia cells, compared to either single-agent treatment." (PMID 31157223, 2019). "Because the orthologous human BASP1 promoter has a similar structure, and BASP1 is downregulated in a variety of human leukemia cells containing elevated MYC levels, human BASP1 transcription may be repressed by a similar mechanism." (PMID 31058089, 2019). "Genetic and shRNA-mediated silencing of BRD4 in MLL-AF9 driven leukemia models not only resulted in the removal of BRD4 from super-enhancers, including the MYC enhancer, but also in differentiation of leukemia cells and decrease of leukemogenic potential in vitro and in vivo." (PMID 31552175, 2019). "Since proscillaridin A induced gene expression and phenotypic changes, we hypothesized that it triggers epigenetic effects in high MYC-driven leukemia." (PMID 31196146, 2019). "Interestingly, proscillaridin A exhibited a strong anticancer activity on both lymphoid and myeloid leukemic stem cell populations overexpressing MYC, indicating the potential of controlling leukemia self-renewal capacity." (PMID 31196146, 2019). "MYC is a potent driver in leukemia inducing cell proliferation and blocking cell differentiation." (PMID 31196146, 2019). "Moreover, inhibited c-MYC protein expression played a critical role in tetrandrine-induced leukemia cell differentiation." (PMID 29700286, 2018). "Moreover, a small molecular c-MYC inhibitor, 10058-F4, enhanced the tetrandrine-induced differentiation of leukemia cells." (PMID 29700286, 2018). "The resulting leukemias were associated with c-MYC upregulation but did not develop NOTCH1 mutations." (PMID 28872614, 2017). "SP1 and MYC can modulate drug resistance of leukemia stem cells." (PMID 28684851, 2017). "Likewise, the SUMO pathway and its regulators such as SENPsULPs and STUbL are therapeutically valuable in a number of cancers, including leukemia and those overexpressing the MYC oncogene." (PMID 27398807, 2016). "Another mechanism of c-MYC regulation is through FBXW7 (F-box and WD repeat domain containing 7, E3 ubiquitin protein ligase), which plays a key role in c-MYC protein degradation in a Thr58-dependent manner, and this mechanism has been shown to play a critical role in leukemia-initiating cells." (PMID 27253416, 2016). "Notably, WNT-β-catenin signaling has previously been shown to be important for cancer stem cell maintenance, and blocking WNT targets in this model not only re-sensitized the leukemia cells to JQ1 but also led to re-suppression of c-MYC." (PMID 27283767, 2016). "Moreover, the exquisite activity of shikonin in U937 cells has been confirmed in other acute leukemia cell lines, implying inhibition of c-MYC as a general mechanism of shikonin and derivatives towards leukemia cells." (PMID 26472107, 2015). "We found c-MYC expression is negatively correlated with MYCBP2 expression in ALL; and high c-MYC expression and/or low MYCBP2 expression is associated with high-risk leukemia." (PMID 26517351, 2015). "Therefore, our data suggests that CK2 inhibitors exert their anti-leukemia effect through Ikaros-mediated suppression of c-MYC expression and activation of MYCBP2 expression." (PMID 26517351, 2015).
leukemia (continued). "In our preclinical in vivo studies, JQ1 demonstrated efficacy against leukemias with deregulated MYC, and this effect was lost when MYC was expressed under a heterologous promoter, indicating that downregulation at the Myc promoter is a major mechanism mediating JQ1 activity in these experiments." (PMID 25956709, 2015). "Consistent with our results, increased accumulation of MYC is responsible for the loss of leukemic stemness in leukemia-initiating cells lacking FBXW7." (PMID 25669969, 2015). "Recently, c-MYC is closely correlated to drug resistance in leukemia cells." (PMID 26472107, 2015). "High c-MYC and/or low MYCBP2 or low Ikaros expression is correlated with high-risk leukemia." (PMID 26517351, 2015). "The role of BCL-2 in tumorigenesis was further confirmed in Eμ-Myc/Eμ-Bcl-2 double transgenic mice where mice that overexpressed both MYC and BCL-2 became terminally ill from leukemia within 50 days while mice that solely expressed MYC required up to 100 days to succumb to malignancy." (PMID 23369605, 2013). "In leukemia, EGR-1 has been implicated in the apoptosis of myeloma cells via interaction with c-JUN while it behaves as a tumor suppressor against the oncogenes E2F-1 and c-MYC." (PMID 22461839, 2012). "MYC’s role as a central node in the oncogenic signaling network means that its inhibition could amplify the effects of menin inhibitors, leading to a collapse of the transcriptional programs that sustain leukemia." (PMID 39682203, 2024). "Here, we tested the hypothesis that deregulation of the centrosome cycle, along with excessive proliferation, caused by overexpression of oncogenic MYC or aberrant expression of ABL tyrosine kinase, can accelerate lymphomagenesis or leukemia formation, respectively." (PMID 38552015, 2024). "Other studies implicated MYC, a well-characterized TF with strong oncogenic potential, in the transcriptional regulation of CD47 during the progression of leukemia using MYC-induced T cell acute lymphoblastic leukemia mouse model; MYC T-ALL, and human leukemia cells lines; CCRF-CEM and Jurkat." (PMID 39742254, 2024). "In addition, a case study showed that amplification of MYC on ecDNA coincided with deletion of MYC on chromosomes from patients with leukaemia, suggesting that ecDNA may originate from chromosomal DNA deletions." (PMID 37448518, 2023). "However, the resistant leukemias showed a rapid return of MYC transcription." (PMID 34298959, 2021). "In human leukemia cells, c-MYC could shift from an eccDNA to an intrachromosomal site." (PMID 33867825, 2021). "Moreover, combination of imatinib with iHDACs has shown promising results in MYC-mediated leukemia." (PMID 34372899, 2021). "Mechanistically, genetic perturbation of CARM1 in the context of leukemia impairs cell-cycle progression, promotes myeloid differentiation, and ultimately induces apoptosis, probably by targeting pathways of proliferation and cell-cycle progression, that is, E2F-, MYC-, and mTOR-regulated processes." (PMID 31657716, 2019). "Thus, FTO could be suppressed by R-2HG in sensitive leukemia cells to elevate global m6A RNA modification, which destabilizes the MYC/CEBPA transcripts and reduces their expression." (PMID 31921664, 2019). "Therefore, targeting MYC addiction in leukemia is a major therapeutic goal." (PMID 31196146, 2019). "In addition, Notch and c-MYC could also be connected through regulatory loops involving microRNA (mostly microRNA 30a) in B and T leukemia." (PMID 29903986, 2018). "In leukemia, c-MYC overexpression may be caused by translocation or amplification implying that the control normally exerted by NHEIII1 through stable G-quadruplex structure is abolished, thereby freeing TF binding sites that could promote c-MYC expression." (PMID 27551915, 2016). "Thus, PIM family members accelerate leukemia in cooperation with MYC in this mouse model." (PMID 25238262, 2014).
leukemia (continued). "High expression of JUP, NT5C3B, MYC, GATA3, PTK7, CNP, and ICOSLG clearly differentiated the leukemia from the non-leukemia group." (PMID 41596324, 2026). "Statistically significant differences between the leukemia and MRD-negative groups were achieved by JUP, NT5C3B, MYC, GATA3, PTK7, CNP, SNAI1, and ICOSLG." (PMID 41596324, 2026). "As expected, reduced MYC expression and chromatin distribution in ∆SET leukemia cells were restored by exogenous MYC expression." (PMID 40341256, 2025). "In leukemia, GAS6 AS1 binds directly to YBX1, promoting its interaction with MYC and resulting in the activation of MYC target genes associated with leukemia progression." (PMID 40799245, 2025). "Both FB23 and FB23-2 suppress leukemia progression by selectively blocking FTO and restoring the m6A profile of MYC, CEBPA, RARA, and ASB2 genes." (PMID 41157107, 2025). "Returning to the NCI-60 Screen data, RNASeq analysis revealed that the leukemia lines, which were most sensitive to DL78, had on average significantly higher MYC expression than 7 other cancers, excluding colon." (PMID 41173942, 2025). "High MYC and CD34 expression define T-ALL cells with leukemia-initiating cell (LIC) properties in activated NOTCH1-driven T-ALL13,66." (PMID 40319015, 2025). "Mechanistically, G9a-i likely reduce H3K9me2 levels at the MIR100HG locus, specifically upregulating the embedded miRNA let-7a-2 to suppress the MYC pathway, which is crucial for the survival of SETD2-mutant leukemia." (PMID 40300107, 2025). "Given the established role of let-7a in MYC suppression, these findings suggest a potential mechanism by which G9a inhibitors induce MYC downregulation in SETD2-mutant leukemia." (PMID 40300107, 2025). "Together, these findings support the conclusion that the MYC signature, a subset of the SETD2 LOF leukemia transcriptomic signatures, is a critical indicator of the actual efficacy of the predicted drug candidates." (PMID 40300107, 2025). "In gene set enrichment analysis (GSEA) DOT1L-ko HEL cells had lost leukemia stem cell (LSC) features, MYC-targets and the expression of KMT2A target genes." (PMID 40781484, 2025). "The use of small-molecule inhibitors targeting FTO affected the expression levels of downstream genes such as MYC, CEBPA, RARA, and ASB2, thereby exerting anti-leukaemia effects." (PMID 39641872, 2024). "For example, in a mouse model of MYC-driven leukemia, BCL2A1 can cooperate with MYC to accelerate leukemogenesis." (PMID 38205232, 2024). "TRIM19 lacking a nuclear localization signal enhances the transcription of BCL2 and MYC proto-oncogenes and the bHLH transcription factor (MYC) and downregulates BAX, thereby inhibiting leukemia cell apoptosis." (PMID 38225560, 2024). "High MYC and CD34 expression define T-ALL cells with leukemia-initiating cell (LIC) properties in activated NOTCH1-driven T-ALL5,17,66,67." (PMID 38352301, 2024). "MYC is a well-known driver of AML pathogenesis and promotes leukemia stem cell (LSC) self-renewal and chemotherapy resistance." (PMID 39376992, 2024). "For example, the transcription factor MYC, which plays a role in the JAK/STAT signalling pathway, is up-regulated in Ph + ALL and contributes to the survival and proliferation of leukemia cells." (PMID 38836918, 2024). "MYBMIM led to MYB-p300 dissociation, suppression of MYB activity followed by downregulation of MYC and BCL2, apoptosis induction in AML cells, and prolonged survival in patient-derived MLL-rearranged leukemia mouse model." (PMID 38835346, 2024). "In AML, IGF2BP2 regulates key targets in the glutamine metabolic pathway (e.g., MYC, GPT1, and SLC5A6) in a m6A-dependent manner, promoting the development and self-renewal of leukemia stem/initiation cells." (PMID 39295872, 2024).
leukemia (continued). "Similarly, IGF2BPs were reported to promote leukemia progression by maintaining the stability of m6A-labeled oncogenic mRNAs encoding self-renewal regulators HOXB4 and MYB, aldehyde dehydrogenase ALDH1A1, the stem cell reprogramming factor LIN28B (which downregulates let-7 miRNA), and c-MYC." (PMID 39497033, 2024). "YBX1 interacts with m6A readers IGF2BPs through its conserved cold shock domain to indirectly bind m6A‐modified mRNA, thereby enhancing the stability of apoptosis‐related genes MYC and BCL2, which in turn sustains the function of leukemia cells." (PMID 39445003, 2024). "I-BET 151 induced G1 phase cell-cycle arrest and apoptosis for mixed lineage leukemia (MLL), achieved by reducing the binding of BRD4 to the promoter regions of MYC, BCL2, and CDK6." (PMID 38539460, 2024). "The well-established therapeutic target BRD4 is a member of the bromo- and extra-terminal domain (BET) family, which activates MYC’s enhancers, thereby maintaining its high oncogenic overexpression in KMT2A-r leukemia and other cancers." (PMID 37036970, 2023). "In leukemia, METTL14, which is negatively regulated by SPI1, exerts its oncogenic effects by regulating m6A modification of its mRNA targets (e.g., MYB and MYC)." (PMID 37932821, 2023). "Mutated Notch1 co-occupies the distal enhancer region of the MYC promoting activation of NFkB signaling, Hes1, PTEN, and PI3K/Akt pathways in a feed-forward loop circuit that supports leukemia cell growth, proliferation, and self-renewal." (PMID 35173274, 2022). "For instance, the m6A writer, METTL3 was found to promote the translation of c-MYC and BCL2 to accelerate leukemia progression by suppressing differentiation and apoptosis in acute myelocytic leukemia." (PMID 35646049, 2022). "In mouse tal1 tumour cell lines, leukaemia growth/survival remains dependent on the NOTCH1-c-MYC pathway; accordingly, the oncogenic functions of c-MYC and NOTCH1 have been established and a direct connection between NOTCH1 and c-MYC was revealed." (PMID 35681778, 2022). "This miRNA has been associated with drug resistance, and it is an essential driver of KMT2A-AFF1 leukemia, integrated with the aberrant overexpression of key downstream targets, i.e., the antiapoptotic factor BCL2 and proto-oncogene MYC." (PMID 36010971, 2022). "We previously found that MSI2 maintains MLL-leukemia self-renewal programs by retaining the translation of HOXA9, c-MYC, MYB, and IKZF218,31." (PMID 36167829, 2022). "The chemical KSI-3716, which blocks c-MYC-MAX binding to DNA, can also suppress cancer cell proliferation in leukaemia." (PMID 35267559, 2022). "METTL14 has also been reported in leukemia; METTL14 exerts oncogenic effects by regulating its mRNAs (MYB and MYC) through m6A modifications." (PMID 35487915, 2022). "Altogether, these results further demonstrated that FTO and its downstream targets (e.g., MYC, RARA) are the major effectors of SsD in FTO overexpressed leukemia cells." (PMID 33897884, 2021). "Next, we assessed the effects of the combined expression of MYC, HOXA9, and MEIS1 in mouse leukemia models." (PMID 34310280, 2021). "In the case of MLL fusion-mediated leukemia, MLL fusion proteins directly activate both MYC and HOXA9, while HOXA9 maintains expression of MYC, BCL2, and SOX4, achieving high MYC activity and anti-apoptotic properties simultaneously." (PMID 34310280, 2021). "As previously reported, MYC is indeed essential for NOTCH1 activity in T-ALL, and inhibiting Myc expression via a BRD4 inhibitor effectively killed leukemia-initiating cells." (PMID 34771671, 2021). "JQ1 can selectively repress MYC transcription in blood malignancies and is active against MLL3-suppressed leukemias resistant to conventional chemotherapy." (PMID 34298959, 2021). "Oncogenic drivers in human leukemia including MYC and RAS are major operative factors in the metabolic rewiring of leukemia cells." (PMID 34868994, 2021).
leukemia (continued). "MYC, BCL2 rearrangements are rarely reported in precursor B-lymphoma/leukemia which carry dismal prognosis." (PMID 34307232, 2021). "For example, R-2-hydroxyglutarate (R-2HG), produced by mutant isocitrate dehydrogenase 1/2 enzymes, was recently found to be able to restrain leukemia cell proliferation and induced cell apoptosis by targeting FTO/m6A/MYC/CEBPA signaling." (PMID 33611339, 2021). "It should be noted that single gene transduction of MYC and SOX4 induced leukemia by others in different settings, albeit with low penetrance." (PMID 34310280, 2021). "In turn, this should mean that, in glioma just as in leukemia, tumours with high FTO levels and low/medium MYC levels should be the most sensitive ones to R-2HG treatment." (PMID 32316617, 2020). "For example, a query of tumor-specific enhancer regions that regulate the expression of the MYC proto-oncogene identified seven up-stream regions in the colon cancer HCT-116 cell line and two enhancer regions down-stream of MYC in the leukemia K562 cell line." (PMID 32448403, 2020). "Most recently, it has been reported that FTO plays a carcinogenic role through the FTO/m6A/MYC/CEBPA signaling pathway in IDH mutant cancers, such as glioma and leukemia." (PMID 32211315, 2020). "HAP1 cells originate from experiments to induce pluripotency in the leukemia KBM7 cell line by transduction with KLF4, POU5F1 (Oct4), SOX2, and MYC." (PMID 33228647, 2020). "A novel oral BRD2/3/4 inhibitor (OTX015) has been shown to reduce MYC expression and to increase HEXIM1 levels in MLL-rearranged leukemia." (PMID 32102485, 2020). "R-2HG can inhibit leukemia and glioma through the regulation of R-2HG-FTO-m6A axis to MYC/CEBPA expression and downstream pathways." (PMID 33304380, 2020). "METTL3 was up-regulated in acute myeloid leukemia cells, enhanced translation of c-MYC, BCL2, and PTEN mRNAs, blocks cell differentiation and apoptosis, and promotes leukemia progression." (PMID 33363011, 2020). "Using both human and mouse BETi-sensitive or BETi-resistant leukemia cells, we identified a BETi-resistance specific enhancer within the PVT1 locus, which facilitated MYC expression in BETi-resistant cells." (PMID 32029739, 2020). "Molecular blockers can inhibit the subunits of MLL-FP complexes such as KMT2A-ENL to downregulate MYC expression, which is crucial for MLL-r leukemia." (PMID 33302406, 2020). "For example, YTHDF2 facilitated c-MYC and CEBPA mRNA degradation by binding to the m6A site in 5'UTR and coding region of c-MYC and CEBPA mRNA, resulting in leukemia cell proliferation." (PMID 32850334, 2020). "METTL14 catalyzed the m6A modification in oncogenic factors MYC and MYB, increasing their mRNA stability and thus maintaining the stemness of leukemia stem cells." (PMID 32101138, 2020). "Ro demonstrates in vivo inhibition of c-MYC and reduces disease burden in a murine AML leukemia model." (PMID 31217428, 2019). "The BASP1 gene is downregulated in many human tumor cell lines particularly in those derived from leukemias, which display elevated levels of WT1 and of the major cancer driver MYC." (PMID 31058089, 2019). "Depletion of ENL results in down-regulation of key leukemic drivers such as MYC, cell growth inhibition, reduced expression of the leukemia stem cell signature, and terminal differentiation of MLL-r leukemia cell models." (PMID 31157223, 2019). "In leukemia, downregulation of RBM25 allows premalignant or malignant cells to harvest the pro-proliferative benefits of MYC (via expression of the BIN(+12) isoform), while at the same time escaping apoptosis (via a shift towards the anti-apoptotic BCL-XL)." (PMID 30635567, 2019). "It’s reported that c-MYC contributes to drug resistance in AML and inhibition of c-MYC induces differentiation, apoptosis, and cell cycle arrest in leukemia cells." (PMID 31519186, 2019).